KRT17 (keratin 17)
Diseases named in the same sentence as KRT17 in open-access papers (continued):
Sharing a sentence is not in itself a finding about the gene and the disease.
psoriasis (continued). "In contrast, keratin expression in psoriasis highlights distinct stress-responsive keratins—including Keratins 6A-C (KRT6A-C), Keratin 16 (KRT16), and Keratin 17 (KRT17)—which serve as molecular markers indicating keratinocyte activation and cellular stress responses." (PMID 41479908, 2025). "QPCR analysis revealed that knockdown of LINC01206 led to increased expression of hyperproliferation markers KRT6, KRT16, and KRT17, suggesting that LINC01206 may promote aberrant keratinocyte proliferation in psoriasis." (PMID 40670887, 2025). "It has been established that KRT17 is not expressed in normal skin but is induced in large amounts in skin stress states, such as skin injury, viral infections and psoriasis." (PMID 37929023, 2023). "Furthermore, several proteins, such as KRT17, KRT17, TWEAK, PCSK9, and ANGPTL4, are highly expressed in psoriasis and tumors and are involved in the development of these two diseases, and knockdown of these proteins exhibits therapeutic effects." (PMID 37762693, 2023). "Further psoriasis and AD share the KRT6A, KRT6B, KRT6C, KRT16, KRT17 as their common DEGs." (PMID 35874668, 2022). "In psoriasis, IL-17, IL-22and INF-3 stimulate keratin 17 overexpression." (PMID 32795328, 2020). "In addition, KRT17 peptides can also serve as autoantigens to activate APC-T cells, leading to the generation of the pathological auto-reactive T cells that drive psoriasis." (PMID 31374826, 2019). "KRT17 is expressed under various pathological conditions, including psoriasis and cutaneous allergic reactions but is not found in healthy epidermis." (PMID 30061793, 2018). "Furthermore, serum levels of moesin, keratin 17 (K17), annexin A1 (ANXA1), and stress-induced phophoprotein-1 (STIP1), which were detected as autoantigens, were studied by dot blot analysis with psoriasis patients and healthy controls." (PMID 25010044, 2014). "Keratin 17, a myoepithelial keratin, is expressed under various pathological conditions, including psoriasis and cutaneous allergic reactions, and is not found in healthy epidermis." (PMID 24962779, 2014). "Similarly, KRT17 acts as a key epithelial activation marker prominently expressed during Th1-mediated inflammatory conditions such as psoriasis, but is notably absent in predominantly Th2-driven disorders like AD." (PMID 41479908, 2025). "Psoriasis, a multifactorial inflammatory condition, has prompted a growing interest in RNA-based therapies, particularly siRNA and miRNA approaches targeting STAT3, keratin 17, and TNF-α pathways, which aim to normalize keratinocyte behavior, suppress inflammation, and modulate angiogenesis." (PMID 40724842, 2025). "The active ingredients of the three tea alcoholic extracts could modulate multiple signaling pathways through a variety of target proteins such as TNF-α, IL-17, FLG, Cytokeratin 17, IL-23, STAT3, FLG, IFN-γ, IL-22, etc., and thus attenuate or inhibit psoriasis." (PMID 38542915, 2024). "Overexpression of the active form of STAT3 in psoriasis leads to increased numbers of IL-17–producing cells and mediates the production of IL-23, resulting in the amplification of the Th17 pathway, while STAT1 stimulates the upregulation of keratin 17 expression." (PMID 37597582, 2023). "Indeed, miR-486-3p is not expressed allowing Keratin 17 protein overexpression and leading to the pathogenesis of psoriasis." (PMID 33712719, 2021). "Therefore, KRT17 is not a suitable marker in the ex vivo psoriasis skin model, although it was a good marker in the in vitro psoriasis model." (PMID 33801280, 2021). "Four of the top six keratins (Krt16, Krt17, and Krt6a and b) that were increased in mice lacking epidermal Pparg are keratins that are known to serve as alarmins and are up-regulated in wound healing and psoriasis." (PMID 34445339, 2021).
psoriasis (continued). "Several peptides derived from the KRT17 protein have been identified to serve as an autoantigen to stimulate T cells in psoriasis, and these KRT peptides are now recognized as the major target antigens recognized by autoreactive T cells isolated from psoriasis patients." (PMID 31374826, 2019). "Another study noted that down-regulation of Keratin 17 expression could inhibit the proliferation of T cells and the production of interferon γ(IFN-γ) effectively in psoriatic cases, which means that Keratin 17 could be used as a new target for the treatment of psoriasis." (PMID 25874882, 2015). "Studies have shown that KRT17, but not KRT6 or KRT16, plays a role in driving keratinocyte hyperproliferation during wounding or psoriasis." (PMID 31374826, 2019).
breast carcinoma (66 papers, 2006 to 2025). "The induction of keratin 17 (KRT17) has been implicated in the antitumoral IL-17-signaling pathway, and its high expression is reported as a favorable prognosis in breast cancer patients." (PMID 40429863, 2025). "KRT17 is notably overexpressed in various cancers, including gastric, cervical, oral squamous cell carcinoma, and breast cancer with TERTp mutations." (PMID 39078811, 2024). "A subset of basal breast cancer classifier genes are connected to the cytokeratin gene KRT17 in BRCA_M14.n7 encompassing genes associated with epithelial and epidermal differentiation and linked to normal-like breast cancer classification." (PMID 30993001, 2019). "Activation of S100A9 is also associated with breast cancer metastatic progression, whereas KRT17 is a potent oncogene." (PMID 28886030, 2017). "Furthermore, the expression of several cytokeratin genes such as KRT5, KRT6B, KRT14, and KRT17 was associated with basal-like breast cancer, a breast cancer subtype that is highly associated with poor treatment outcome." (PMID 35911770, 2022). "Similarly, upregulation of KRT17 has been used as a diagnostic marker for several cancers, such as breast cancer, ovarian cancer and skin squamous carcinoma." (PMID 36009022, 2022). "Although KRT17 has been confirmed to be associated with breast cancer in clinical studies, it has not been confirmed in cell and animal experiments so far, and its mechanism of action in breast cancer cells needs to be further confirmed." (PMID 35281081, 2022). "Six of the 11 non-mitosis related genes were previously associated with poor survival in breast cancer patients: KRT17, MMP12, SLC7A5, SQLE, GABRP and PA2G4, but the remaining 5 had not been previously associated with cancer risk: CCDC86, NUP107, NUTF2, WASF1 and ELOVL6." (PMID 23077491, 2012). "The expression levels of VIM, KRT5 and KRT17 in normal samples were significantly higher than those in breast cancer samples." (PMID 38581422, 2024). "For example, it has been shown that KRT17 and KRT5 were significantly upregulated in basal-like breast carcinomas, and the overexpression of KRT17 was associated with poor prognosis of cancer." (PMID 37468850, 2023). "Considering that the proportion of triple-negative breast cancer cases included in TCGA is small (approximately 14% of all breast cancer cases), high expression of KRT17 seems to indicate a good prognosis." (PMID 35646078, 2022). "KRT17 was found to be overexpressed in several cancers, including breast cancer and cervical cancer." (PMID 33441834, 2021). "Basal-like breast cancer (BLBC) is a subtype of breast cancer defined by gene expression profiling and it is characterised by the expression of genes related to basal epithelial cells such as keratin 5, keratin 17, integrin-β4 and laminin." (PMID 29380207, 2018). "Because STAT3 influence cancer cell ability for invasion and migration and microarray analysis in canine mammary tumor cells showed downregulation of Keratin 17 due to MDSC co-culture, we examined a role of IL-28 in EMT." (PMID 25075523, 2014). "While there is little information on the role of KRT15 in breast cancer, KRT17 expression was studied in 600 breast tumors and was shown to be associated with poor clinical outcome." (PMID 20543960, 2010). "WalBC cells exhibited expression of known markers of basal invasive human breast cancers as well as increased KRT17, KRT 14 and KRT 19, DSP, s100A4, NDRG-1, ANXA1, TK1 and AQP3 gene expression and decreased gene expression of TIMP3, VIM and TAGLN." (PMID 18179684, 2008). "In comparison with those consistently classified as basal-like (n = 46), the tumors clustered as ERBB2 (n = 12) showed a lower average expression in KRT17, KRT5 and especially GABRP, which has been reported to be associated with ER-/HER2- breast cancers." (PMID 16846532, 2006). "KLF5 was coexpressed with basal markers (KRT5, KRT14 and KRT17) in breast cancer tissue." (PMID 36923542, 2023).
breast carcinoma (continued). "Moreover, according to HPA results, KRT17 is over-expressed in cervical and head and neck cancers and represents a favorable prognostic marker for breast cancer." (PMID 36949761, 2023). "However, the Kaplan–Meier plotter indicated that high expression of KRT17 has good prognostic implications in breast cancer." (PMID 35646078, 2022). "Keratin KRT17, belonging to type I keratin, was regenerated and highly expressed in many cancers, including gastric cancer, cervical cancer, oral squamous cell carcinoma, and breast cancer." (PMID 32560331, 2020). "In particular, KISS1 is a gene suppressing melanoma (MEL) and breast cancer (BC) metastasis, and KRT17 shows up-expression that may be related to skin lesions and acts as a promoter of epithelial proliferation by regulating immune response." (PMID 28824643, 2017). "Two of the 3 LAR models were KRT5 and KRT17 negative at the protein level, Vimentin was highly expressed in 2 out of 3 metaplastic breast cancer, which also showed loss of E-cadherin expression." (PMID 27374081, 2016). "It was reported that KRT17 could be a tumor marker in squamous cell carcinoma of head and neck and breast cancers." (PMID 25874882, 2015). "A total of 44 human breast cancer cell lines and three immortalized breast epithelial lines were categorized as representing luminal or basal breast cancer subtypes based on the relative gene expression of cytokeratin 8/cytokeratin 18 and cytokeratin 5/cytokeratin 17, respectively." (PMID 19874578, 2009). "Similarly, KRT5, KRT6, KRT14, and KRT17 are known to be expressed by both breast cancer and SKCM." (PMID 35267493, 2022). "It is odd that KRT17 is linked to kinase signaling for normal tissue and not for a breast cancer subtype, when this has been described for another cancer but this may be associated to tumor incidence over adjacent tissue." (PMID 32528899, 2020). "In addition, four cytokeratin genes (KRT8, KRT16, KRT17, and KRT19) and eight tumor-associated genes (TERT, MUC16/M17S2/CA125, CD44, TWIST1, TACSTD1/EpCAM/CD326/ESA/HEA125/GA733, DPP4/CD26, ESR1, and PGR), were upregulated in CRC and breast cancer samples." (PMID 29882767, 2018). "And studies have confirmed that KRT17 can activate the ERK signaling pathway in bladder and breast cancer and promote cancer progression." (PMID 40860436, 2025). "Among the types of BC, KRT17 is a marker of triple-negative breast cancers (TNBCs), and overexpression of KRT17 has been confirmed to be associated with poor prognosis in estrogen receptor (ER)−/HER2− BC patients." (PMID 36139022, 2022). "Rather, the neo-expression of KRT17 in conventional RCC can be used as a predictive biomarker similar to gastric, ovarian or breast carcinoma 11-16." (PMID 31602265, 2019). "Classification of primary breast cancer RNASeq data based on high/low CEBPB/REST/CTCF revealed that, KRT5, KRT14 and KRT17 mRNAs were significantly upregulated in CEBPBhigh and CTCFlow tumors." (PMID 30335837, 2018). "Four genes from breast cancer stage III network pattern (KRT8, KRT17, KRT18 and HOXC10) physically interact with EGFR, a target gene of Lapatinib Breast cancer drug which is quite similar (greater than 50%) to Paroxetine (repurposed drug from LINCS)." (PMID 26892392, 2016). "In this study, up-regulation of Keratin 17 (KRT17) and down-regulation of Keratin 15 (KRT15) were observed in breast cancer." (PMID 20543960, 2010). "Some genes associated with cell adhesion were analyzed from this radiation- and estrogen-induced experimental breast cancer model, including E-cadherin gene CDH1, DSC3, GJA1, the Integrin alpha 6 gene ITGA6, the Integrin beta 6 gene ITGB6, the Keratin genes KRT14, KRT16, KRT17, KRT6B, and LAMB3." (PMID 36293530, 2022). "Expression of KRT17 has also been found in several other types of cancer such as gastric adenocarcinoma, ovarian and breast carcinoma, papillary thyroid carcinoma but not in their corresponding normal tissue 11-16." (PMID 31602265, 2019).
breast carcinoma (continued). "Furthermore, some of the most well-known genes for basal-like breast cancer, such as keratin 5 and keratin 17, were not even significantly different between our TN and non-TN samples." (PMID 22140552, 2011). "Surprisingly, anillin overexpression did not decrease protein levels of E-cadherin, P-cadherin, and keratin 17 in MCF10AneoT cells (data not shown), indicating that high anillin expression alone is not sufficient to trigger significant de-differentiation of epithelial-type breast cancer cells." (PMID 31910867, 2020).
cervical carcinoma (39 papers, 2008 to 2025). A carcinoma arising from either the exocervical squamous epithelium or the endocervical glandular epithelium. "KRT17 (keratin 17) has been reported to be overexpressed not only in bladder cancer but also in other types of cancers such as breast, cervical, oral, esophagus, pancreatic and colon cancers, and associated with poor prognosis of breast and cervical cancers." (PMID 30214686, 2018). "In addition, it has been shown that high levels of KRT17 expression in cervical cancer are associated with poor prognosis and cancer cell differentiation, and that KRT17 could be used as a prognostic biomarker." (PMID 35706019, 2022). "Keratin 17 has also been reported as a potential diagnostic marker for oral squamous cell carcinoma, and it might be linked to the clinical progression and differentiation of cervical carcinoma." (PMID 22140553, 2011). "KRT17 confers increased resistance to cisplatin in cervical cancer and bladder cancer, and elevated expression of this gene was described to correlate with poor survival in oropharyngeal squamous cell carcinoma." (PMID 39358322, 2024). "KRT17 is upregulated in various types of tumors, including oral cancer, breast cancer, non-small cell lung cancer and cervical cancer." (PMID 35706019, 2022). "Our team found that KRT17 expression was significantly different before and after cervical cancer radiotherapy when screening radiotherapy sensitivity genes (GSE6213)." (PMID 35646078, 2022). "In cervical cancer cell lines, KRT17 knockout decreased the viability and migration ability of cervical cancer cells and down-regulated Snail2 and up-regulated E-cadherin." (PMID 35281081, 2022). "KRT17 was found to play a key role in advancing cervical cancer development and paclitaxel-induced mediate resistance." (PMID 36248412, 2022). "Studies have shown that during the occurrence of cervical cancer, the expression of some inflammatory cytokines and immune cytokines in tumors is significantly dependent on KRT17." (PMID 35646078, 2022). "It is suggested that the high expression of KRT17 is invasive, and the treatment of the high expression of KRT17 in cervical cancer patients should be cautious in clinical practice." (PMID 35281081, 2022). "In recent years, studies have shown that KRT17 is abnormally expressed in a variety of malignant tumours, such as lung cancer, cervical cancer, oral squamous cell carcinoma and sarcoma." (PMID 35281081, 2022). "For example, KRT17 impacts the pathogenesis of cervical cancer by promoting the nuclear transport and degradation of protein P27 (Kip1)." (PMID 36248412, 2022). "Prior to our current study, KRT17 was reported to correlate with CSCs in a few cancers such as cervical cancer and urothelial carcinoma." (PMID 35706019, 2022). "KRT17 was found to be highly expressed in cervical cancer, esophageal cancer, lung cancer, gastric cancer, and colorectal cancer cell lines." (PMID 35646078, 2022). "KRT17 knockout was also found to inhibit cell proliferation and migration and increase sensitivity to cisplatin chemotherapy in cervical cancer cells." (PMID 35646078, 2022). "We found that the expression of Ki67 was increased according to histopathological stage, whereby high expression of KRT17 was specifically found in cervical cancer and low expression of CRISP2 was specifically observed in HSIL." (PMID 33624385, 2021). "Most importantly, we found that expression of KRT17 was stronger than that of Ki67 in cervical cancer, indicating that KRT17 is a more specific and suitable marker for cervical cancer." (PMID 33624385, 2021). "As a downstream factor of the TGF‐β1‐/ERK1/2‐/MZF1 signalling pathway, KRT17 has been shown to promote metastasis through enabling the acquisition of tumour microenvironment related cancer stem cell (CSC) properties in cervical cancer." (PMID 32537856, 2020).